AR (androgen receptor)
Diseases named in the same sentence as AR in open-access papers (continued):
Sharing a sentence is not in itself a finding about the gene and the disease.
bladder cancer (continued). "In addition, enzalutamide treatment or AR knockdown was shown to inhibit the growth of gemcitabine-resistant bladder cancer cells, while whether it could increase chemosensitivity was not tested." (PMID 28241422, 2017). "In particular, androgen-mediated androgen receptor signals have been shown to correlate with the promotion of tumor development and progression, which may clearly explain some sex-specific differences in bladder cancer." (PMID 28241422, 2017). "We further found that AR inactivation could increase sensitivity to CDDP in bladder cancer cells." (PMID 27322140, 2016). "Emerging preclinical evidence has suggested a critical role of androgen receptor (AR) signaling in inducing urothelial carcinogenesis and cancer progression, which may explain the gender-specific difference in the incidence of bladder cancer." (PMID 27322140, 2016). "Thus, androgen appeared to activate NF-κB via the AR pathway in bladder cancer cells." (PMID 27322140, 2016). "The effect of GRβ on AR guided proinflammatory pathways in bladder cancer remains unknown." (PMID 26347776, 2015). "Targeting of AR may potentially be a good therapy for bladder cancer in males." (PMID 26347776, 2015). "EGF could also induce bladder cancer cell proliferation via modulating AR signals." (PMID 26770009, 2015). "Thus, AR activation is likely required for the regulation of bladder cancer cell growth by ELK1." (PMID 26342199, 2015). "However, there is evidence of AR induced bladder cancer in females." (PMID 26347776, 2015). "Furthermore, we highlight several molecules regulated by AR and/or ER signals in bladder cancer cells, which may contribute to the development of diagnostic and/or prognostic biomarkers." (PMID 26770009, 2015). "In the present study, we investigated whether EGF could alter AR activity in bladder cancer cells." (PMID 22922989, 2012). "In particular, the androgen receptor (AR) and estrogen receptor (ER) signaling pathways have been shown to contribute to bladder tumorigenesis and cancer progression, which may explain some of the differences in male versus female bladder cancer." (PMID 22922989, 2012). "Indeed, in many bladder cancer tissue specimens, AR and ER(s) were found to be co-expressed." (PMID 22922989, 2012). "Moreover, several types of cancers originated in non-reproductive tissues, such as lung cancer, bladder cancer, melanoma, and glioblastoma, have been associated with the activation of androgens/AR signaling pathways for proliferation or enhancing survival of cancer stem cells." (PMID 41228208, 2025). "In cultured bladder cancer cells, PEDF expression negatively correlates with AR expression, and while androgen upregulates AR, it does the converse to PEDF." (PMID 40649783, 2025). "Based on the findings in DNA microarray analysis in control AR-positive vs. AR-knockdown bladder cancer sublines we had previously performed, we anticipated that GABBR2 functioned as a downstream target of AR." (PMID 37762034, 2023). "Our DNA microarray analysis in control vs. AR-knockdown bladder cancer sublines suggested that the expression of a GABA B receptor GABBR2 and AR was correlated." (PMID 37762034, 2023). "Specifically, AR activation in bladder cancer cells has been shown to result in the induction of CDDP resistance, and AR knockdown or antiandrogen treatment thus enhances its sensitivity." (PMID 37762034, 2023). "Specifically, androgen treatment and AR knockdown/antiandrogen treatment induced and reduced, respectively, the levels of GABBR2 expression in bladder cancer cells." (PMID 37762034, 2023). "We herein determined the relationship between AR activity and GULP1 expression in bladder cancer cells and then assessed the functional role of GULP1 in cisplatin sensitivity." (PMID 34576193, 2021). "The LSD1-JMJD2 complex with activated AR removes the methylation of histones and pharmacologic inhibition of LSD1 suppresses androgen induced transcription and bladder cancer cell growth." (PMID 33919565, 2021).
bladder cancer (continued). "Our results demonstrate that AR signals in UCC favouring the development of an aggressive phenotype and highlights its potential as a therapeutic target for bladder cancer." (PMID 33797847, 2021). "A knock down of XIST showed a decrease in AR protein expression and repressed cell proliferation; this means that XIST regulates AR expression, and both function as oncogenes in bladder cancer." (PMID 33919565, 2021). "In addition, because BXDC2-negative/AR-positive tumors were strongly associated with resistance to CDDP-based chemotherapy, the expression status of BXDC2, along with that of AR, might serve as a predictor of chemosensitivity in patients with bladder cancer." (PMID 33652650, 2021). "Epidermal growth factor was reported to activate the androgen receptor and increase the expression of TRIP13 to promote bladder cancer progression." (PMID 34374227, 2021). "In the present study, we further investigated the role of GULP1, as a downstream target of AR, in CDDP resistance, using bladder cancer cell lines as well as surgical specimens." (PMID 34576193, 2021). "Specifically, AR overexpression/androgen treatment and AR knockdown/anti-androgen treatment reduced and induced, respectively, the levels of GULP1 expression in bladder cancer cells." (PMID 34576193, 2021). "After confirming an increase in AR activity in CR-T24 cells, we utilized the KDM7A inhibitor TC-E 5002, in conjunction with AR antagonist enzalutamide, to evaluate the role of KDM7A on bladder cancer growth and drug resistance in terms of the AR pathway." (PMID 32781788, 2020). "The T24 bladder cancer cells expressing control or KDM7A shRNA were treated with DHT, sonicated, and the chromatin was precipitated with AR antibody." (PMID 32781788, 2020). "In the presence of androgens, AR and β-catenin were shown to co-express in the nuclei of BCC and form a complex with TCF leading to the progression of bladder cancer." (PMID 31027362, 2019). "While the precise mechanisms of the functions of the androgen receptor in urothelial cells remain far from being fully understood, current evidence may offer chemopreventive or therapeutic options, using androgen deprivation therapy, in patients with bladder cancer." (PMID 28241422, 2017). "In CDDP-resistant bladder cancer sublines established following long-term culture with CDDP, the expression levels of AR as well as NF-κB and phospho-NF-κB were considerably elevated, compared with respective control sublines." (PMID 27322140, 2016). "We assessed the effects of androgen on ELK1 expression by reverse transcription (RT)-polymerase chain reaction (PCR), western blotting, and immunofluorescence in bladder cancer cells treated with DHT and/or an AR antagonist hydroxyflutamide (HF)." (PMID 26342199, 2015). "We have recently shown that AR signals increase EGFR and ERBB2 expression and activity, suggesting androgen-mediated bladder cancer progression via the regulation of the EGFR/ERBB2 pathways." (PMID 22922989, 2012). "In contrast, the relationship between the AR and EGFR pathways in bladder cancer remains poorly understood." (PMID 22922989, 2012). "Furthermore, AR signaling promotes epithelial-mesenchymal transition (EMT) and metastasis in bladder cancer through the Wnt pathway and upregulation of the transcription factor Slug." (PMID 40458476, 2025). "As seen in BBN-treated AR knockout mice where DHT induced bladder cancer development, a recent study demonstrated preclinical evidence suggesting the presence of the DHT-mediated pathway other than that via classical AR." (PMID 40486871, 2025). "In addition, one study suggests a role of androgen/AR signaling in phosphorylation of eIF4E, which can promote EMT in bladder cancer cell lines." (PMID 41463239, 2025). "A chromene derivative 2j, which could function as a selective inhibitor for AKR1C3, was found to inhibit the expression of AR and ELK1 in bladder cancer cells and enhance the cytotoxic activity of gemcitabine + cisplatin." (PMID 40486871, 2025).
bladder cancer (continued). "Although the interaction of PPARG with AR in bladder cancer remains uninvestigated, evidence suggests that PPARG affected bladder cancer development and progression by regulating metastasis, apoptosis, proliferation and reactive oxygen species (ROS) and lipid metabolism." (PMID 40458476, 2025). "Previous studies suggested that AR activation induced resistance to conventional non-surgical therapy for bladder cancer, including intravesical BCG immunotherapy, intravesical or systemic chemotherapy, and radiotherapy." (PMID 40486871, 2025). "This work suggests a novel mechanism partly explaining the inverse relationship between AR and bladder cancer tumor progression and suggests that AR and CD44 expression may be useful for prognostication and therapeutic selection in primary bladder cancer." (PMID 38539529, 2024). "The contribution of AR signaling to female bladder cancer diagnoses is not well understood; therefore, initial efforts to utilize anti-androgens for secondary bladder cancer prevention will likely initially occur in men." (PMID 38398136, 2024). "The present study aimed to explore whether gamma-aminobutyric acid (GABA) B receptor 2 (GABBR2), which belongs to the G protein-coupled receptor superfamily, functions as a downstream effector of AR and induces resistance to CDDP therapy in bladder cancer." (PMID 37762034, 2023). "In a meta-analysis of AR protein expression studies, AR expression was found to be similar to normal uroepithelial cells in bladder cancer cells and was not significantly elevated." (PMID 37328487, 2023). "According to multiple studies, androgens stimulate bladder cancer growth via classical and non-classical AR pathways." (PMID 38283839, 2023). "In the present study, we aim to investigate whether GULP1, an adaptor protein known to facilitate phagocytosis, represents a downstream effector of AR and thereby modulates CDDP sensitivity in bladder cancer." (PMID 34576193, 2021). "In the present study, we further investigated the role of BXDC2, whose expression could be downregulated by AR, in CDDP resistance, using bladder cancer cell lines as well as surgical specimens." (PMID 33652650, 2021). "In the bladder cancer cells TCC-SUP, EJ, SW780, and UM-UC-3, XIST and AR are up-regulated." (PMID 33919565, 2021). "We first examined the expression of BXDC2 in 4 human bladder cancer lines that were known to be AR-negative (i.e., 5637, 647V) or AR-positive (i.e., UMUC3, TCCSUP)." (PMID 33652650, 2021). "Thirteen to fifty-three percent of bladder cancer specimens express the androgen receptor (AR), regardless of the patient’s sex." (PMID 34206980, 2021). "We first examined the expression of GULP1 in four human bladder cancer lines that were known to be AR-negative (i.e., 5637, 647V) or AR-positive (i.e., UMUC3, TCCSUP)." (PMID 34576193, 2021). "In this article, we mainly reviewed preclinical and clinical data implying the involvement of sex hormone receptors, particularly AR and ER signals, in modulating sensitivity to conventional non-surgical therapy for bladder cancer." (PMID 34064926, 2021). "The expression of AR and BXDC2 in bladder cancer lines and tissue specimens was then found to be inversely correlated, suggesting that BXDC2 could be a downstream effector of AR." (PMID 33652650, 2021). "In bladder cancer, XIST has been found to be up-regulated parallel with up-regulation of AR." (PMID 34831421, 2021). "The following are key molecules whose expression and/or activity have been shown to be modulated via the androgen-AR/estrogen-ERβ/glucocorticoid-GR signaling pathways in non-neoplastic urothelial (or bladder cancer) cells." (PMID 32759680, 2020). "More specifically, the incidence of bladder cancer was significantly lower in male mice lacking AR only in urothelial cells than in wild-type littermates, suggesting a critical role of urothelial AR in bladder tumorigenesis." (PMID 32759680, 2020).
bladder cancer (continued). "In the same study, striking increases in CD24 expression by androgen treatment were observed in AR-positive bladder cancer lines, although no such changes in non-neoplastic urothelial cells have been demonstrated." (PMID 32759680, 2020). "A subsequent study showed that surgical or chemical castration or AR antagonist flutamide treatment reduced the occurrence of bladder cancer in BBN-treated male rats, while no combination effect was observed." (PMID 32759680, 2020). "We investigated the expression of androgen receptor in human bladder cancer cell lines T24, HTB9, and HT1376 as well as a nonmalignant transitional epithelial cells of the ureter HCV29 by Western blotting." (PMID 31119584, 2019). "Our results indicate that non-genomic signals involving AR in bladder cancer likely diverge at the level of cytoplasmic and plasma membranes." (PMID 31119584, 2019). "In a separate set of experiments, mice engineered to not express AR in urothelial cells were found to have a lower incidence of bladder cancer following exposure to the carcinogen BBN [N-butyl-N-(4-hydroxybutyl)-nitrosamine]." (PMID 28085048, 2017). "Non-androgen-mediated AR activation in bladder cancer cells and androgen-induced tumorigenesis via the non-AR pathway have also been documented." (PMID 28362839, 2017). "Further investigations are required to determine the effects of anti-AR therapy on chemosensitivity, especially in animal models for bladder cancer, and to elucidate the precise mechanisms of how AR signals involve CDDP resistance in bladder cancer cells." (PMID 27322140, 2016). "In contrast, AR expression correlated with the progression of bladder tumors, while others did not reveal its prognostic significance in patients with bladder cancer." (PMID 26770009, 2015). "Androgens also failed to significantly induce AR transcriptional activity in ELK1 knockdown bladder cancer cells." (PMID 26770009, 2015). "The communication between the AR and EGFR pathways may play a role in the male prevalence in bladder cancer." (PMID 26347776, 2015). "AR signals activate CD24, a glycoprotein and a cell adhesion molecule, in bladder cancer cells." (PMID 26770009, 2015). "Although some bladder cancer lines are known to possess a functional AR, FK506 (and CsA) similarly inhibited the growth of AR-positive (i.e. UMUC3, TCCSUP) versus AR-negative (i.e. 647V, 5637) bladder cancer cells." (PMID 25638160, 2015). "Of note, activated AR is necessary for ELK1 to promote bladder cancer cell proliferation, but not cell migration." (PMID 26342199, 2015). "Using a profiling array kit, activities of 96 known transcription factors were compared in AR-positive bladder cancer UMUC3 cells with versus without a non-aromatizable synthetic androgen methyltrienolone (R1881) treatment." (PMID 26342199, 2015). "We additionally found that ELK1 silencing induced apoptosis of bladder cancer cells that possessed a functional AR and were cultured with FBS containing androgens but did not modulate the cell-cycle status." (PMID 26342199, 2015). "Repeatedly, the AR expression increased by androgen with or without EGF in bladder cancer cells was abolished by an AR antagonist." (PMID 22922989, 2012). "In bladder cancer cells, we here showed that EGF could activate AR transcription and PD168393, a specific inhibitor of EGFR, restored this EGF effect." (PMID 22922989, 2012). "We have recently shown that AR activation results in upregulation of EGFR and ERBB2 expression in bladder cancer cells, which may play an important role in androgen-mediated tumor progression." (PMID 22922989, 2012). "By contrast, several other studies could not find gender related differences for AR expression in bladder cancer." (PMID 41463239, 2025). "However, we found that androgen does not regulate the progression of bladder cancer through the AR pathway." (PMID 37328487, 2023).
bladder cancer (continued). "Additionally, it has been found that androgen receptor-mediated signaling inhibits UGT expression in bladder and prostate cancer, indicating a gender bias in the UGT detoxification pathway in bladder cancer." (PMID 38283839, 2023). "To further elucidate how AR signals modulate chemosensitivity in urothelial cancer, we here investigated the functional role of a potential downstream effector, BXDC2, known to involve ribosome biogenesis, using bladder cancer cell lines and surgical specimens." (PMID 33652650, 2021). "This could suggest that the AR may participate in the development of bladder cancer, but not to be a determining factor." (PMID 33919565, 2021). "Androgen receptor signaling is involved in bladder cancer, although this pathology is not considered sex-related, because the higher associated risk in men versus women may reflect other aspects, nor is the bladder considered an androgen-responsive organ." (PMID 33919565, 2021). "The significant impact of CD24 knockdown in male mice on the rate of BBN-induced bladder cancer development was not seen in female mice (wild-type: 33% vs. CD24-deficient: 24% at 16 weeks), implying the involvement of AR signaling in CD24-mediated urothelial tumorigenesis." (PMID 32759680, 2020). "Androgen receptor has been detected in human BC in a number of studies but it is not clear whether its expression level is important in bladder cancer progression." (PMID 31119584, 2019). "They provided the first in vivo evidence that AR in urothelium might play a crucial role in initiation and progression of urinary bladder cancers in genomic and non-genomic way." (PMID 31119584, 2019). "Indeed, the CpdA that selectively induces transrepression has been shown to inhibit not only cell migration/invasion of bladder cancer but also the cell proliferation of even AR-negative bladder cancer lines, primarily via the GR pathway." (PMID 30518063, 2018). "Meanwhile, up-regulation of ROR in AR knockdown cells may imply androgen action via the non-AR pathway or the presence of the second AR in bladder cancer cells, which requires further studies." (PMID 26342199, 2015). "Importantly, ELK1 appears to require activated AR to regulate bladder cancer cell proliferation, but not cell migration." (PMID 26342199, 2015). "This shows that the use of antiestrogen therapy may be useful in treating bladder cancer; however, ERβ has not been shown to be a driver of bladder cancer, while AR's driving capability has been demonstrated." (PMID 26347776, 2015). "Additionally, mRNAs from two human bladder cancer cell lines have revealed AR sequences with short CAG repeat lengths, suggesting that altered mRNA sequences of the AR gene could contribute to bladder cancer." (PMID 26347776, 2015). "However, crosstalk between AR and EGFR pathways in bladder cancer remains uncharacterized." (PMID 22922989, 2012). "While AR signaling plays an important role in the substantial male sex bias observed in bladder cancer, it is important to acknowledge non-biological factors (e.g., social, behavioral, occupational, environmental) and biological explanations other than the androgen receptor as well." (PMID 38398136, 2024). "In addition, androgens have a high affinity to prostate tissue through the androgen receptors (AR), which can significantly influence the physiological state of prostate tissues and facilitate BPH development, and trigger the occurrence of various bladder carcinomas." (PMID 36468030, 2022). "The MLPA assay did contain sequences to analyze a limited number of genes, but of several exons; some genes that may have an important role in bladder cancer progression were not included in this assay, e.g. the androgen receptor, which may contribute to disease progression by EGFR signaling." (PMID 33298978, 2020). "EGF could also induce AR-positive bladder cancer cell proliferation in the absence of androgens." (PMID 28241422, 2017).